BRAF (B-Raf proto-oncogene, serine/threonine kinase)
Diseases named in the same sentence as BRAF in open-access papers (continued):
Sharing a sentence is not in itself a finding about the gene and the disease.
melanoma (continued). "In case of BRAF-mutated melanoma, additional first-line options are provided by BRAFis and MEKis." (PMID 39550033, 2025). "Thus, ICIs have become the standard of care in BRAF wild-type melanoma and in BRAF mutated melanoma after resistance to BRAF inhibitors." (PMID 40004220, 2025). "As a redox protein, the p66Shc expression differs among subtypes of melanomas, which may correlate with tumour invasiveness and/or genetic backgrounds, including BRAF mutation status." (PMID 40690563, 2025). "The discrepancy in tumor location between BRAF- and NRAS-mutated melanomas can be attributed to the differing sensitivity of BRAF- and NRAS-mutant melanocytes to ultraviolet (UV) light-induced carcinogenesis, with BRAF-mutated melanocytes exhibiting greater sensitivity to UV-mediated damage." (PMID 39857682, 2025). "Likewise, BRAF V600E mutations in melanoma or colorectal cancer identify patients eligible for BRAF/MEK inhibitor combinations." (PMID 41301080, 2025). "Melanomas with BRAF mutations are generally considered more aggressive and more therapy-resistant." (PMID 41465443, 2025). "The introduction of targeted therapies, including BRAF inhibitors (e.g., vemurafenib (VEM) and dabrafenib) and MEK inhibitors (e.g., trametinib (TRA) and cobimetinib), has marked a significant therapeutic advancement for patients with BRAF-mutated melanoma over the past decade." (PMID 40558540, 2025). "Additionally, ALDH2 expression levels in BRAF-mutated metastatic melanoma cells influence cell sensitivity to BRAF and MEK inhibitors, with low ALDH2 expression associated with both intrinsic and acquired resistance." (PMID 40558540, 2025). "Melanoma cells harboring BRAF mutations exhibit a heightened dependence on leucine; consequently, leucine deficiency may impede autophagy within tumor cells, suggesting a potential novel strategy for immunotherapy." (PMID 40539068, 2025). "However, NRAS-mutant melanoma, a subtype comprising 15–25% of melanomas, remains refractory to most current treatments and is associated with a poorer prognosis compared to BRAF-mutant or wild-type variants." (PMID 40563669, 2025). "Patients with BRAF-mutated melanomas were younger than those with BRAFWT melanomas." (PMID 41010758, 2025). "The hypothesis behind the lack of co-existence involves the pathogenesis of melanoma where either an NRAS or BRAF mutation occurs during the initial development of melanoma and remains stable throughout the disease course." (PMID 39940799, 2025). "SIRT2 downregulation was also linked with BRAF/MEK inhibitor resistance in BRAF-mutant melanoma." (PMID 39935431, 2025). "In this respect, ATOX1 is critical for the activation of the MEK-ERK signaling pathway in BRAFV600E-mutated melanomas, as the pharmacological inhibition of ATOX1 by DC_AC50 decreases the phosphorylation of ERK1/2 and reduces the growth of BRAF-mutated melanoma cells." (PMID 40721800, 2025). "Additionally, melanomas that develop on skin surfaces with signs of cumulative sun damage, like marked solar elastosis, show a low frequency of BRAF V600E mutations, but these cases show the less commonBRAF V600K mutation." (PMID 40507250, 2025). "For example, tumors with specific mutations, such as BRAF mutations in melanoma, may respond better to certain therapeutic combinations." (PMID 41153631, 2025). "Similarly, personalized cancer vaccines that target neoantigens specific to BRAF-mutated melanoma are under investigation." (PMID 39897423, 2025). "In addition, targeted therapies directed at BRAF, a gene mutated in 50% of melanomas and responsible for activating the MAPK/ERK-signaling pathway implicated in melanomagenesis, have demonstrated highly encouraging results in phase I, II, and III trials." (PMID 40361518, 2025). "However, unlike cancers driven by recurrent targetable mutations, such as BRAF V600E in melanoma, leiomyosarcomas typically exhibit a low tumor mutational burden and a paucity of actionable genetic alterations." (PMID 41199835, 2025).
melanoma (continued). "Besides the important pathogenic mechanisms of melanoma, including BRAF-driven and immunosuppressive microenvironment, genomic instability and abnormal DNA double-strand breaks (DSB) repair are significant driving forces for its occurrence and development." (PMID 39885134, 2025). "The findings of this study suggest that LA could serve as a prospective future nutraceutical candidate for controlling melanoma and other malignancies with BRAF mutations." (PMID 39795195, 2025). "This study assessed gut microbiota composition and immune-associated genes in melanoma, to generate hypothesis on prognostic and predictive biomarkers for BRAF/MEK inhibitor therapy." (PMID 40659866, 2025). "Similarly, the development of resistance to BRAF inhibitors in melanoma has been shown to be linked to the upregulation of Notch signaling, while inhibiting this signaling pathway resensitized the cancer to the targeted therapy." (PMID 40574005, 2025). "First, our experimental models primarily reflect features of acral melanoma and the identified high-risk TEAD3 + subgroup; thus, the generalizability to other melanoma subtypes (e.g., BRAF or NRAS mutant, or triple wild-type tumors) requires further validation." (PMID 41034991, 2025). "Besides the spectrum of genetic alterations which are associated to BRAF/MEKi resistance, metabolic rewiring and profound epigenetic changes characterize melanoma plasticity and treatment resistance." (PMID 41550951, 2025). "Her medical history included melanoma of the skin treated by wide local excision, malignant melanoma of the breast and axillary lymph nodes treated with surgical resection followed by nivolumab immunotherapy, a positive BRAF mutation and a right cochlear implant." (PMID 41552174, 2025). "In BRAF-mutant melanomas, the microphthalmia-associated transcription factor (MITF) positively regulates the expression of miR-579-3p, which in turn downregulates BRAF, stabilizes MITF protein, and induces its own transcription in a positive feedback regulatory loop." (PMID 39805813, 2025). "In melanoma, BRAF mutations are early and significant in nearly 50% of cases." (PMID 39795195, 2025). "For instance, BRAF-mutated melanoma cells might continue to produce via triggering glycolysis following BRAF inhibitor therapy." (PMID 40917751, 2025). "Notably, previous reports of GA associated with melanoma have involved metastatic disease and systemic therapies such as BRAF inhibitors or immune checkpoint inhibitors." (PMID 41030925, 2025). "However, in melanoma cells that harbor a BRAF V600E mutation, expression of EGFR ranges from a low of 0.8 up to 3.1 which is well above the expected expression levels of EGFR." (PMID 40869231, 2025). "However, other studies have found statistically significant results, although they identified different aspects as more frequent in BRAF-mutated melanomas compared to BRAF-wild-type melanomas." (PMID 41010758, 2025). "Similarly, combining p66Shc inhibitors with ROS‐inducing agents enhances apoptosis in melanoma with BRAF mutations, suggesting broader applicability across cancer types." (PMID 40690563, 2025). "It is also well established that treatment with anti-PD-1/anti-CTLA-4 combination in the 1L setting in the BRAF-mutated melanoma patients results in better outcomes when compared to the use of targeted therapy, as demonstrated in the SECOMBIT and DREAMseq trials." (PMID 40027067, 2025). "Furthermore, in our study, BRAF-mutated melanomas tended to have higher Breslow thickness and higher mitotic rate." (PMID 40867317, 2025). "MAPKi-resistant BRAF-mutated melanoma also shows increased FAO and peroxisome biogenesis." (PMID 40617808, 2025). "BRAF mutations were more commonly identified in melanoma (p < 0.001)." (PMID 40867302, 2025). "Mutations in NRAS and BRAF are present in approximately 80% of the most common melanomas." (PMID 41170188, 2025).
melanoma (continued). "Stage I melanoma had higher odds of being BRAF mutated than stage II melanoma." (PMID 40902091, 2025). "The LOGIC-2 trial (NCT02159066) evaluated the efficacy of adding one of four other agents including ribociclib (CDK4/6i) to encorafenib (BRAFi) and binimetinib (MEKi) in 38 patients with advanced BRAF V600-mutated melanoma who progressed on encorafenib and binimetinib." (PMID 40282469, 2025). "The BRAF mutational status is crucial in selecting systemic therapy for advanced melanoma." (PMID 41010758, 2025). "Senescence also plays a dual role in therapy resistance: genotoxic therapies such as carboplatin/paclitaxel induce senescence in melanoma cells, rendering them susceptible to Bcl2 inhibitors, while targeted BRAF/MEK inhibition produces senescent-like cells resistant to such treatments." (PMID 40781676, 2025). "Moreover, the IMspire150 study demonstrated that the addition of PD-1 monoclonal antibody to targeted therapy was well tolerated and significantly improved PFS in advanced melanoma patients with BRAF V600E mutation." (PMID 41225509, 2025). "Additional mutated driver genes in melanoma other than BRAF, such as NF1 and NRAS, might also impact the treatment choice." (PMID 40004220, 2025). "Mutations in the Raf-MEK-ERK mitogen-activated protein kinase (MAPK) cell proliferation signalling pathway, including BRAF, NRAS and KIT mutations, are frequently detected in patients with malignant melanoma; the BRAF mutation rate in the Japanese population is about 30%." (PMID 39918770, 2025). "In melanoma or other malignant diseases, the occurrence of BRAF mutations may significantly modulate the tumor microenvironment (TME) by directly affecting tumor cells and immune cells." (PMID 41160271, 2025). "Patients with BRAF-mutated melanomas were younger than those with wild-type melanomas." (PMID 41010758, 2025). "In our population, we could only treat BRAF wild-type melanoma in the 1L setting with immunotherapy monotherapy (mainly anti-PD-1) and the BRAF-mutated melanoma with BRAFi/MEKi." (PMID 40027067, 2025). "Mutations in RAF are quite prevalent in human cancer (BRAF mutations are present in about 6% of human cancers), and are responsible for many different types of cancer, including colorectal cancer, melanoma, breast cancer, ovarian cancer, thyroid cancer, and prostate cancer." (PMID 40943615, 2025). "In parallel, BRAF/MEK inhibitors are another key therapeutic option for BRAF-mutated melanoma." (PMID 41294692, 2025). "The most important ‘driver’ mutation of melanoma is a mutation in BRAF." (PMID 40902091, 2025). "Notably, mucosal melanoma exhibits distinct molecular characteristics compared to its cutaneous counterpart, such as a lower BRAF mutation rate and a higher prevalence of NF1 mutations, which restrict the applicability of targeted therapies." (PMID 40969261, 2025). "This combination therapy is indicated in patients with BRAF V600 mutated melanoma." (PMID 40004731, 2025). "In addition, CDK4 and CCND1, cell cycle regulators that are frequently mutated or amplified in BRAF wild-type melanomas, were included." (PMID 40647405, 2025). "The chemokine CCL2, known to be involved in tumor progression and metastasis, has been studied as well, demonstrating that BRAF-targeted therapy decreases CCL2 gene expression and secretion, correlated with reduction in tumor size in a specific murine model of BRAF-mutated melanoma." (PMID 40872623, 2025). "MiR-193a-3p is associated with the presence of BRAF mutations in melanoma." (PMID 41515546, 2025). "CES1 expression and high SAG, 2-AG, and ARA levels may be a signature of specific BRAF-driven malignant melanoma subtypes which are associated with discrete metabolic adaptations." (PMID 39934865, 2025). "For BRAF-mutated melanomas, the options include immunotherapy (nivolumab or pembrolizumab), or a combination of dabrafenib and trametinib may be considered." (PMID 40933889, 2025).
melanoma (continued). "Initially discovered in melanoma, BRAF mutations have since been identified across a wide spectrum of malignancies, including non-small-cell lung cancer (NSCLC), colorectal cancer (CRC), thyroid cancer, gliomas, other rare cancers, and various hematologic and pediatric tumors." (PMID 40332392, 2025). "In melanoma, BRAF mutations are detected in 50–70% of cases." (PMID 40332392, 2025). "The BRAF V600K mutant melanoma is more frequently associated with older age, male gender, and scalp location and have demonstrated more-aggressive behaviour than BRAF V600E, with an inferior response to treatment and shorter progression-free survival after a combination of BRAF and MEK inhibitors." (PMID 40507250, 2025). "Anti‐PD1‐treated patients with a BRAF V600 mutation had a shorter RFS than patients with BRAF WT melanoma (p < 0.01); this was validated in external data where the presence of a BRAF V600 mutation was associated with an increased hazard recurrence (HR: 2.1, p = 0.025)." (PMID 41342263, 2025). "Additionally, a recent Dutch registry study investigated outcomes of either anti‐PD1 or BRAFi/MEKi therapy in 646 patients with a BRAF mutated melanoma and stage III disease." (PMID 41342263, 2025). "Therefore, understanding the intricate molecular mechanisms governing PTEN loss and its effect on BRAF inhibitor resistance is pivotal for optimizing melanoma treatment strategies." (PMID 40129883, 2025). "Moreover, considering the success of dual inhibition in BRAF V600E-mutated melanoma BMs, further clinical trials focusing on the intracranial efficacy of dabrafenib and trametinib in BRAF-mutated NSCLC BM are warranted." (PMID 39998776, 2025). "The COMBI-AD phase III trial demonstrated that patients with resected stage III BRAF-mutated melanoma who received dabrafenib and trametinib as adjuvant therapy had longer relapse-free survival (RFS) and distant metastasis-free survival compared to those receiving placebo." (PMID 40861441, 2025). "The reported BRAF mutation in Romanian melanoma patients is similar to that in other countries." (PMID 40361989, 2025). "It is highly effective in about half of patients with BRAF-mutated melanoma." (PMID 40932870, 2025). "Also, in melanoma patients with any BRAF mutation, pre-approval mOS was 14.2 months (n=1), and post-approval mOS ranged from 15.9 to 51.2 months (n=6; with mOS not reached for n=3)." (PMID 40831930, 2025). "Indeed, patients with untreated BRAF V600 mutated melanoma have a worse prognosis than patients with BRAF wild-type tumors." (PMID 39673834, 2025). "Approximately, 50% of melanomas carry BRAF mutations (90% are V600E)." (PMID 40869231, 2025). "BRAF gene mutation is common in over 60% malignant melanomas." (PMID 39891180, 2025). "Statement 9: For patients with clinically detectable stage III melanoma harboring a BRAF V600 mutation, neoadjuvant systemic therapy with BRAF-targeted therapy for a duration of 8-12 weeks may be considered as an alternative to immunotherapy." (PMID 40857557, 2025). "However, in melanoma, dysregulation frequently arises due to activating mutations in the BRAF and RAS genes, as well as other genetic and epigenetic alterations." (PMID 40427124, 2025). "Interestingly, we found that the presence of a BRAF mutation significantly impacts the long-term survival of melanoma patients with brain metastasis." (PMID 40028330, 2025). "This study uncovers an essential interplay between the eIF4F translation initiation complex, which contributes to melanoma resistance, and the extracellular signal-regulated kinase (ERK) signaling pathway, the primary therapeutic target in melanomas with BRAF and NRAS mutations." (PMID 39436655, 2024).
melanoma (continued). "The main driver mutations in the MAPK pathway in melanoma are the BRAF and NRAS genes." (PMID 39272885, 2024). "The use of high sensitivity methods without established cut-off points and the presence of a different, undiagnosed neoplasm with a high prevalence of BRAF mutations (e.g., melanoma and colorectal cancer) may contribute to false positivity." (PMID 39336882, 2024). "In treatment-naive melanoma, BRAF mutations shape distinct immune landscapes." (PMID 39582535, 2024). "BRAF mutant melanoma cancers carry a high co-mutation burden (of which many gene alterations are of unknown significance)." (PMID 38275886, 2024). "Additionally, it is well known that primary melanomas can arise from different driving mutations, such as those in BRAF or NRAS." (PMID 39062529, 2024). "BRAF mutations are characteristic of ordinary naevi and melanomas." (PMID 38390852, 2024). "The National Authority for Assessment and Accreditation in Healthcare (INEAS), the Health Technology Assessment (HTA) body in Tunisia, conducted a de novo cost-effectiveness analysis of vemurafenib for the treatment of locally advanced or metastatic BRAF V600-mutated melanoma in Tunisia." (PMID 39464179, 2024). "Such a result suggests that not only RIPK4 but also other features, such as BRAF mutation status, may influence the sensitivity of melanoma cells to cisplatin." (PMID 39766280, 2024). "The EZH2 mutational status may indeed impact sensitivity to BRAF inhibition, providing a potential explanation for the development of resistance to BRAF inhibition in certain melanoma cases." (PMID 39304771, 2024). "Similarly, the rate of BRAF V600K mutations is higher among desmoplastic melanomas and other melanomas associated with chronic sun-damaged skin." (PMID 39001457, 2024). "In addition, LY3009120 has been broadly applied in tumor cells or colorectal carcinoma xenograft models harboring oncogenic RAS or BRAF mutations and Vemurafenib-resistant melanoma cells as well as tumor cells with oncogenic BRAF deletions." (PMID 38397192, 2024). "BRAF/MEK inhibitor resistance is linked to alterations of melanoma lipid pathways." (PMID 38338838, 2024). "The overall survival rate for therapy-naive BRAF-mutated advanced melanoma patients is 34% after 5 years of combined targeted therapy with BRAF/MEK-inhibitors, whereas patients receiving a first-line immune checkpoint blockade showed an overall 5-year survival rate of 60%." (PMID 39125519, 2024). "Moreover, depletion or pharmacological inhibition of USP7 dampens cell migration and invasion and increases melanoma susceptibility to BRAF inhibitors." (PMID 39135915, 2024). "Also, there were significantly more CAFs in mutant BRAF melanomas versus NRAS melanomas; and increased CAF frequency was associated with more recurrence." (PMID 38525245, 2024). "In this paper, we report about the discovery of a novel mechanism controlling BRAF-mutated melanoma progression which involves the interplay between the well-known microphthalmia-associated transcription factor (MITF) and the recently discovered oncosuppressive miR-579-3p." (PMID 38472212, 2024). "The extracellular signal-regulated kinase (ERK) signal transduction pathway, which regulates cell proliferation, differentiation, and survival in response to extracellular stimuli, is constitutively activated in most malignant melanomas due to oncogenic mutations of NRAS or BRAF genes." (PMID 39436655, 2024). "Notably, the efficacy of this treatment approach is independent on BRAF mutational status of melanoma cells." (PMID 38182748, 2024). "Additional genetic alterations or environmental factors may be necessary for a nevus with a BRAF mutation to transform into melanoma." (PMID 38534742, 2024).